BDNF (brain derived neurotrophic factor)
Diseases named in the same sentence as BDNF in open-access papers (continued):
Sharing a sentence is not in itself a finding about the gene and the disease.
depression (continued). "Moreover, another group demonstrated anxiety-like and depression-like behaviors in mdx mice, associated with decreased BDNF (Brain derived neurotrophic factor) levels." (PMID 32160266, 2020). "Serum BDNF concentrations have been found to be decreased in patients with depression and diabetes." (PMID 33568996, 2020). "Moreover, a high intake of saturated fatty acids seems to be associated with a lower level of brain derived neurotrophic factor (BDNF), neuroplasticity and cognitive ability, that are involved in the pathogenesis of depression." (PMID 32937855, 2020). "In addition, BDNF plays a role in learning and memory, and its decreased production is a pathogenetic factor of major depression." (PMID 33322180, 2020). "Interestingly, epidemiological and experimental studies point to a potential role of the endogenous NOS inhibitor asymmetric dimethylarginine (ADMA) and BDNF in neuropsychiatric disorders, in particularly in depression." (PMID 33353117, 2020). "While several studies have looked into the relationship between the BDNF gene and MDD in young people, no study has so far investigated the association of BDNF sequence variants in early onset depression." (PMID 32869548, 2020). "PEA ameliorates CORT-induced depression-like behaviors by activating BDNF/TrkB/CREB signaling." (PMID 33265983, 2020). "Furthermore, the ANCOVA revealed significant differences between the depression control group and the depression exercise group in BDNF, NT-3, and NT-4 plasma levels using pre-exercise values as the covariate." (PMID 32210759, 2020). "However, the neurobiology of depression is very complex, involving not only BDNF but also a lot of other members regulated by CREB, such as mammalian target of rapamycin, vascular endothelial growth factor and peroxisome proliferator-activated receptor alpha." (PMID 33519490, 2020). "In current study, significant differences in BDNF were found in all three depression models." (PMID 31867894, 2020). "Furthermore, it was also observed that geniposide increased the BDNF expression to attenuate depression-like behavior and cellular alterations in the hippocampus of streptozotocin-treated mice." (PMID 33613190, 2020). "H2S not only attenuates homocysteine-induced apoptosis in hippocampal neurons and ERS by upregulating the expression of BDNF-TrkB in the MDD model but also improves CUMS-induced depression and inhibits hippocampus by promoting the expression of hippocampal Sirt-1 ERS." (PMID 32477150, 2020). "Considering the different changes in BDNF in stress-related (decreased BDNF in hippocampus) and reward-related systems (increased BDNF in VTA and NAc), stress-induced anxiety and depression may be associated with the degree of activation of different pathways." (PMID 32085670, 2020). "We hypothesize that patients will present alterations in salivary CAR and serum BDNF, which will be positively correlated with depression severity and sleep disturbances." (PMID 32410966, 2020). "Furthermore, the BDNF signaling cascade mediates the role of the hippocampal SIK2-CRTC1 system in the pathogenesis of depression." (PMID 33519490, 2020). "Similarly, in a short review, while providing evidence of shared biological substrates between PD and depression, neuroplasticity was underscored by the roles of BDNF." (PMID 33029119, 2020). "Clinical studies also indicate that BDNF could be an independent prognostic factor of the post-stroke depression." (PMID 31701356, 2020). "Therefore, in this section, we focus on these signaling pathways and discuss the role of the BDNF signaling pathway in hippocampal plasticity in depression and antidepressant drugs." (PMID 33293948, 2020). "In conclusion, our results demonstrate that BDNF in the mPFC is involved in CUS-induced depression-related behavior and increased stress susceptibility in postpartum female mice and postpartum-specific BDNF deletion revealed an important regulatory role of BDNF in depression-related behavior." (PMID 32532322, 2020).
depression (continued). "For instance, decreased plasma levels of BDNF were found in patients with depression." (PMID 33256231, 2020). "Reduction in BDNF levels has been reported in persons with depression." (PMID 33076878, 2020). "The finding of decreased serum BDNF levels in drug-naïve MDD patients may indicate a significant relationship between the pathophysiology of depression and peripheral levels of BDNF." (PMID 32085720, 2020). "The neurotrophic hypothesis of depression suggests BDNF decreases in depression and that antidepressants increase BDNF expression." (PMID 32012861, 2020). "This research demonstrated that plasma BDNF decreased in rats subjected to 15 min forced swimming stress and increased after being treated with paeoniflorin and fluoxetine, as well as relieving depression-like behavior in rats." (PMID 32733578, 2020). "The loss of BDNF in either the DG or CA1 subregion of the hippocampus did not alter depression-related behavior." (PMID 32351365, 2020). "We found that treating BD-II patients with a combination of add-on DM30 + MM5 might attenuate symptoms of depression and raise plasma BDNF levels compared with placebo, but that it had little effect on other cytokines and metabolic profiles." (PMID 32115672, 2020). "Decreased levels of BDNF have been detected post mortem in the cortex, hippocampus and nucleus basalis of Meynert in patients suffering from Alzheimer’s disease, while region-specific down but also upregulation of BDNF has been shown in major depressive disorder patients." (PMID 32944867, 2020). "This is the only one review to investigate, for community-dwelling adults with cognitive impairment, whether group-based multicomponent exercise influence cognition, memory, attention, executive function, depression and the level of BDNF." (PMID 32191630, 2020). "Depression-like behavior of Camk4−/− mice in comparison with wild-type animals is accompanied by a combination of disturbances in the hippocampal dentate gyrus, including inhibition of neurogenesis and a decrease in the activation of BDNF signaling pathway." (PMID 32992988, 2020). "However, the exact function of BDNF in depression of postpartum female mice remains to be investigated." (PMID 32532322, 2020). "Furthermore, BDNF involvement in depression/anxiety disorders has been confirmed through measuring peripheral BDNF levels as well." (PMID 33584494, 2020). "Although there are different phenotypes in anxiety and depression, antidepressants are reported to treat a set of anxiety-related phenotypes, which indicates the existence of shared mechanisms in these two disorders, which probably relies on BDNF." (PMID 32085670, 2020). "Similarly, clinical studies was demonstrated lower serum or plasma BDNF concentration in patients diagnosed with major depression and manifesting suicidal behavior." (PMID 32970734, 2020). "Interestingly, HIIT associated with experimental ischemic stroke models was able to increase neuroplasticity (BDNF) and enhance markers against depression." (PMID 32455608, 2020). "Notably, there is a “BDNF theory of depression” which describes BDNF as the key molecule accounting for the pathological changes underlying the symptoms of depression." (PMID 32326205, 2020). "In addition, restoration of BDNF is also involved in the geniposide- and ellagic acid-mediated alleviation of depression-like behavior in STZ-evoked diabetic mice." (PMID 33568996, 2020). "However, increased BDNF promoter methylation after antidepressant treatment correlated with depression remission." (PMID 32012861, 2020). "In this review, we summarize the latest research, focusing on changes in the plasticity of hippocampal neurons and glial cells in depression and the role of BDNF in the changes in hippocampal plasticity in depression, as well as caloric restriction and mitochondrial plasticity." (PMID 33293948, 2020).
depression (continued). "On the other hand, 12-week structural regular exercise training integrated with aerobic, resistance, and balanced exercise can decrease the BDNF, NT-3, and NT-4 plasma levels that are correlated with the alleviation of depression and anxiety after METH withdrawal." (PMID 32210759, 2020). "BDNF, one of the major neurotrophic factors, plays a role in the pathophysiology of depression." (PMID 32513185, 2020). "Decreased BDNF may relate to the reduced function of the BDNF gene in promoting neural growth and repair in depression." (PMID 32942585, 2020). "It is hypothesized that pathological changes in BDNF expression are responsible for neuropsychological deficits related to stress, depression or suicide." (PMID 32970734, 2020). "Moreover, exercise-mediated production of neurotransmitters, such as dopamine, serotonin, and brain-derived neurotrophic factor, contributes to the treatment of depression." (PMID 33424581, 2020). "This may be due to the release of neurotrophins triggered by PE, such as the brain-derived neurotrophic factor, as people with depression tend to display lower levels of this biomarker than their healthy counterparts, while PE induces its increase." (PMID 32455853, 2020). "Our study suggests that AE may prevent depression through beneficially affecting glucocorticoids, thereby leading to an increase in BDNF expression in the hippocampus." (PMID 33374661, 2020). "Moreover, altered BDNF level is related to increased appetite, obesity, type 2 diabetes, depression, as well as Alzheimer’s and Parkinson’s diseases." (PMID 32012942, 2020). "Since fatigue behaviors can be closely related to problems with cognition and depression, these symptoms may share distinct mechanisms related to BDNF expression." (PMID 32614931, 2020). "There are reports of opposite effects of BDNF in depression-like behaviors depending on brain region, where increased BDNF in the hippocampus and frontal cortex can have antidepressant-like effects and BDNF in the ventral striatum can produce depression-like behaviors." (PMID 32614931, 2020). "In addition, studies in humans showed decreased plasma levels of BDNF in patients with bipolar disorder, mania, and depression." (PMID 33233633, 2020). "However, contradictory findings have been observed regarding serum BDNF and depression, and the evidence for reduced BDNF in patients with AUD remains limited." (PMID 32372985, 2020). "The associations of prolactin and BDNF levels with the presence of depression was non-significant: OR 1.19 (95%CI 0.85; 1.68) for ln(prolactin), and OR 1.03 (95%CI 0.58; 1.84) for ln(BDNF)." (PMID 32116853, 2020). "BDNF has been considered an important biomarker of major depression." (PMID 32410966, 2020). "Notably, the ability of Sigma1R agonists with antidepressant activity, along with normalization of the BDNF level, to restore the Sigma1R level in the brain of animals with comorbid depression has been revealed." (PMID 32992988, 2020). "From the data of this study, we found that decreasing the expression of HCN1 in the animal model of PTSD alleviates PTSD-like symptoms, reducing depression-like symptoms and improving spatial learning ability followed by an upregulation of BDNF–mTOR signaling pathways in the PFC and Hip." (PMID 32198387, 2020). "Insulin also increases BDNF mRNA levels and phosphorylation levels of Akt and GSK3b in a concentration‐dependent manner, thereby enhancing mouse memory in Y‐maze experiments and reducing depression‐like behaviour in forced swimming experiments." (PMID 32281722, 2020). "Furthermore, future studies should further investigate potential mechanisms involved in the association between BDNF, NCAM, and AUD and depression." (PMID 32372985, 2020).
depression (continued). "With regard to the involvement of structural variation of the BDNF gene in the pathogenesis of mood disorders, Ernst et al32 demonstrated that two neurodevelopmental disorder patients with whole‐genome BDNF deletion have been diagnosed as having major depression." (PMID 31769621, 2020). "The aging hippocampus: interactions between exercise, depression, and BDNF." (PMID 32876194, 2020). "Despite a higher risk of depression in Asian and Indian populations, extensive studies targeting polymorphisms in BDNF have never been executed in these populations so far." (PMID 32171272, 2020). "Interestingly, resveratrol administration has been shown to have antidepressant effects in an animal model of depression via the activation of brain-derived neurotrophic factor." (PMID 33372679, 2020). "As for the molecules involved in depression, BDNF is the most well-known." (PMID 33117794, 2020). "Moreover, cumulative knowledge indicates that bee honey increases brain levels of BDNF, resulting in improvement of mood and alleviation of depression." (PMID 33333828, 2020). "Overall, the inhibition of HCN1, which can alleviate PTSD-like behavior of rats by relieving depression and improving learning ability, may be related to the upregulated BDNF-mTOR signaling pathways and synaptic transmission." (PMID 32198387, 2020). "The significance of the lower BDNF levels in depression is currently unclear." (PMID 33096634, 2020). "Moreover, circulating BDNF levels are decreased in patients with stroke, and especially those patients with post-stroke depression and anxiety." (PMID 33233734, 2020). "BDNF levels are also decreased in Alzheimer’s disease, which could support the hypothesis that depression belongs to the spectrum of neurodegenerative diseases." (PMID 33255237, 2020). "We discuss neuroplasticity underscored by the roles of miRNAs and BDNF, which might further reveal the potential biological mechanism of neurodegenerative diseases and depression by acupuncture." (PMID 33029119, 2020). "The impairment of brain-derived neurotrophic factor (BDNF) signaling and serotonergic neurotransmission, as well as the activation of corticosterone action, have been implicated in the pathogenesis of CNS diseases, particularly depression." (PMID 32932690, 2020). "Interestingly, we observed alterations in BDNF-TrkB signaling in the liver from mood disorders including major depressive disorder and bipolar disorder, suggesting a possible role of BDNF-TrkB signaling in mood disorders." (PMID 29882089, 2020). "Thus, the PDK1/Akt pathway has been reported as intermediating in the role of neurotropic factors, like brain-derived neurotrophic factor (BDNF), in the acquisition of fear and mood disorders like depression and anxiety." (PMID 32457586, 2020). "In addition to the biological activity of mature BDNF, proBDNF can also lead to depression by inducing peripheral neuronal apoptosis, while both pro- and mature BDNF exert opposite biological effects in vivo." (PMID 32153441, 2020). "Synaptic plasticity in neuronal networks playing a role in depression is regulated by BDNF." (PMID 32231570, 2020). "Decreased serum BDNF with normal cortisol levels may represent a relevant biomarker for individuals more likely to develop depression." (PMID 33255237, 2020). "A widely accepted “neurotrophic hypothesis”, postulates that a reduction in BDNF expression is involved in the pathophysiology of major depression, while anti-depressant increases the expression of BDNF in hippocampus." (PMID 32171272, 2020). "The rescue of these depression-like behaviors and abnormal synaptic function may be due to changes in BDNF/TrkB signaling, which are downregulated in response to CORT exposure." (PMID 33265983, 2020). "Lower expression of BDNF is difficult to resist the injury of neurons under stress, which could lead to depression." (PMID 33658934, 2020). "Contrariwise, repeated ECS consistently increased brain BDNF level in depression-free animals." (PMID 32153449, 2020).
depression (continued). "In rodents, injection of BDNF in the hippocampus reduces depression-like behavior, in contrast injection of BDNF into the nucleus accumbens or ventral tegmental area promotes depressive effects, demonstrating the network-dependent effect of BDNF in mood regulation." (PMID 33096634, 2020). "Connolly and colleagues have demonstrated increased serum brain-derived neurotrophic factor (BDNF), a neurotrophin with important effects on neurogenesis and neuronal plasticity, in children with epilepsy; whereas lowered levels were detected in depressive disorder." (PMID 32607501, 2020). "Hence, the miR-16/BDNF signalling pathway is involved in depressive disorder and seems to be promising." (PMID 33029119, 2020). "Therefore, a more transdiagnostic approach is required, studying the role of BDNF in single and co-morbid cases of depressive disorder and AUD." (PMID 32372985, 2020). "Moreover, the HPA axis and brain-derived neurotrophic factor (BDNF) have also been widely studied in the context of pathogenesis and treatment of depressive disorders." (PMID 32256358, 2020). "Age, smoking, body composition, physical activity, and depression influence both BDNF and CRF." (PMID 31635145, 2019). "Importantly, major depressive disorder (MDD), as well as diverse neurodegenerative diseases, are associated with reduced levels of BDNF paralleled by diminished GABAergic neurotransmission." (PMID 31484392, 2019). "Given that the candidate targets were mostly involved in the BDNF signaling pathway, ZL may combat depression by acting on this pathway." (PMID 30625977, 2019). "Therefore, further longitudinal studies are needed to better understand the role of BDNF in development of depression in MMD." (PMID 31234814, 2019). "Thus, losartan interferes with the detrimental effects of diabetes on BDNF signalling in the brain, linking diabetes-induced depression with neuroinflammation and the potential role of BDNF in this experimental model." (PMID 31053872, 2019). "Regarding the biological factors, studies of biomarkers such as BDNF may provide insights into the possible mechanisms of illness and recovery from serious disorders such as depression, bipolar disorder, and schizophrenia." (PMID 31024364, 2019). "BDNF is closely related to many neurological diseases such as Alzheimer’s disease and depression." (PMID 31049031, 2019). "Investigation of the effect and potential mechanism of salidroside on depression showed that salidroside could down-regulate the expression of BDNF, TrkB, and the NF-κB protein." (PMID 31231295, 2019). "The “neurotrophic hypothesis” for depression even postulates that a stress-induced decrease in BDNF initiates depression." (PMID 31659205, 2019). "The BDNF as an activity-dependent neuronal plasticity, by reduction of tropomycin receptor kinase (Trk)-B (TrkB) as specific neurotrophin receptors, increased the depression symptoms." (PMID 31234814, 2019). "Thus, Ntrk2b is the major receptor of BDNF in the zebrafish brain and its function is essential in maintaining two important aminergic systems involved in anxiety, stress and depression: the dopaminergic and the serotonergic systems." (PMID 30765816, 2019). "Like BDNF, NGF seems to be negatively associated with depression and suicide." (PMID 30767081, 2019). "In addition, physical activity increases the secretion of BDNF (a neurotic factor produced in the brain), the concentration of which is low in people with depression." (PMID 31480778, 2019). "Patients with depression show lower serum BDNF than healthy controls." (PMID 31438638, 2019). "BDNF abnormalities could contribute to the dysfunction of astrocytes and microglia in depression circuits." (PMID 31234814, 2019). "Taken together with the current results, this suggests BDNF may be one pathway mediating the relationship between religiosity and depression." (PMID 31572245, 2019).